GBP2 (guanylate binding protein 2)
Diseases named in the same sentence as GBP2 in open-access papers (continued):
Sharing a sentence is not in itself a finding about the gene and the disease.
tumor (continued). "Moreover, in most cancer types, GBP2 was favorably connected with TIIC levels but negatively correlated with tumor purity." (PMID 37784054, 2023). "All things considered, GBP2 may be a novel biomarker for determining tumor immunogenicity and directing immunotherapy." (PMID 37784054, 2023). "We focused on GBP2 and revealed its significant role in shaping the tumor microenvironment." (PMID 35937997, 2022). "We therefore investigated the tole of GBP2 in tumor immune microenvironment." (PMID 36186425, 2022). "There are few studies on the relationship between GBP2 and tumor progression." (PMID 35383115, 2022). "Speculating that GBP2 might play a role in the tumor microenvironment, we analyzed its correlation with the CD8+ T cells, the most potent effector cell in immunotherapy." (PMID 35356208, 2022). "The acidosis-related signature is composed of seven key genes (ARNTL2, DKK1, CEP55, CTSV, MYEOV, DSG2, and GBP2), all of which have elevated expression levels in PC tumor tissues compared with normal tissues and are all related to adverse clinical outcomes in patients with PC." (PMID 34993253, 2021). "Thecorrelation observed between tumors methylation status and corresponding plasma,certified that plasma GBP2 methylation pattern could be consideredas a representor of the tumor methylation status." (PMID 33211060, 2020). "GBP2 may consider as a controlling factor in tumor progressionby inhibiting NF-KappaB, Rac and matrix metalloproteinase 9 expressions." (PMID 33211060, 2020). "In addition, it was found that the expression of ARGs was associated with immune cell infiltration and immune checkpoint in ccRCC, among which GBP2 was thought to be the most relevant gene to the tumor immune microenvironment and play a potential role in carcinogenesis and invasion of tumor cells." (PMID 35356208, 2022). "Based on the result derived from GEPIA, the expression of genes, including Cd3e, Cd274 (PDL-1), Wt1, Fate, Gbp2, and Cybb were significantly upregulated in the GBM tumor compared to the normal brain." (PMID 41282050, 2025). "The results of immunochemistry showed that GBP2, HCLS1, P2RX7, and SLC11A1 were more highly expressed in the tumor group than in the normal group." (PMID 41007849, 2025). "Therefore, high GBP2 expression in PAAD may directly support tumor cell proliferation by driving cell cycle progression and may also indirectly modulate the tumor’s response to BA activation by influencing the immune microenvironment or disrupting cell cycle regulation." (PMID 41595468, 2025). "There were substantial differences in CpG methylation in GBP2, SLC11A1, and HCLS1 between tumor and normal samples." (PMID 41007849, 2025). "More importantly, the knockout of GBP2 resulted in a reduction in CD8+ T cell infiltration and blunted the efficacy of PD-1 blockade in tumor-bearing mice." (PMID 38169731, 2023). "Consistent with RNAseq data, GBP2 expression was higher in normal tissues (p = 1.877130e-04), and GBP4 expression was higher in tumor tissues (p = 1.25852508986603e-08)." (PMID 36246628, 2022). "We further confirmed that GBP2 knockout reduced CD8 +T cell infiltration and blunted the efficacy of PD-1 blockade in tumor-bearing mice." (PMID 35383115, 2022). "GBP2 is a guanylate binding protein induced by IFN-γ and is considered as a control factor for tumor cell proliferation and spreading." (PMID 31781157, 2019). "Genes such as CFLAR, EP300, GBP2, HEYL, KLF7, NOTCH1 or POFUT showed a similar correlation with NUMB or NUMBL in the three tumor types considered." (PMID 29507685, 2018). "Three genes, including NETO2, GBP2, and VCAN, showed consistent high expression across these 90 tumor samples." (PMID 24783204, 2014). "However, it is important to consider that anti-tumoral pathways were not solely upregulated, and we observed an increase in the expression of genes such as GBP2 and GBP5, which are known to promote tumor progression and growth." (PMID 40498028, 2025).
tumor (continued). "GBP2 expression is induced by interferon-γ (IFN-γ), which increases the expression of the PD-L1 ligand through the signal transducer and activator of transduction pathway 1 (STAT1), thus promoting tumor immune escape." (PMID 37370817, 2023). "Our results showed that the expression GBP2 was significantly and positively correlated with both the expression of most immune checkpoints (such as PD-1 and PD-L1) and the distribution of CD8+ T cells in the RCC tumor microenvironment." (PMID 35356208, 2022). "In contrast, the expression of GBP1 or GBP2 had minor effect on GBM cell growth in vitro but dramatically induced tumor growth in vivo, indicating these GBPs may modulate tumor microenvironment." (PMID 33608513, 2021). "Notably, CALU, TFRC, and GBP2 were highly expressed in early developmental stages, whereas SERPINB5 and LY6D were up-regulated in later phases, indicating their involvement in distinct stages of cellular state transitions and tumor progression." (PMID 41595468, 2025). "Studies indicate that GBP2 significantly correlates with increased expression of multiple immune checkpoints (including PD-1 and PD-L1) and with CD8+ T cell distribution in the renal cell carcinoma tumor microenvironment, potentially promoting cancer progression." (PMID 41181145, 2025). "In tumor tissues, thefrequency of GBP2 down regulation was 73.2% whereas 26.8% ofbreast cancer patients showed normal expression and none of the tested samplesshowed GBP2 up-regulation." (PMID 33211060, 2020). "ITGAL, GBP1, GBP2 and ITGB2 were all upregulated in TLS positive tumors compared to TLS negative, but no changes could be observed in Tumor versus Normal and TLS positive versus Normal." (PMID 30082828, 2018).
cancer (29 papers, 2010 to 2026). A tumor composed of atypical neoplastic, often pleomorphic cells that invade other tissues. "GBP2 was favorably linked with the expression levels of various immunomodulators, with the exception of a few cancer types." (PMID 37784054, 2023). "The interferon-induced protein known as guanylate-binding protein 2 (GBP2) has been linked to multiple different cancer types as an oncogenic gene." (PMID 37784054, 2023). "Functional analysis demonstrated that positively co-expressed genes of GBP2 were closely associated with pathways in cancer and the NOD-like receptor signaling pathway." (PMID 34026364, 2021). "Furthermore, pan-cancer analysis revealed that GBP2 was associated with activated TIME features in most cancer types." (PMID 37784054, 2023). "GBP2 belongs to the dynamin superfamily of large GTPases, famous for its cell-autonomous immunity against microbial pathogens, inflammation, and cancer development." (PMID 41007849, 2025). "GBP2 was among the highly upregulated genes in H. felis-infected mice, potentially promoting cancer progression by enhancing angiogenesis, proliferation, migration, metastasis, invasion, and tumorigenicity." (PMID 41181145, 2025). "As previously discussed, GBP2 is involved in the regulation of pyroptosis, highlighting its multifaceted role in cell death mechanisms relevant to cancer." (PMID 41181145, 2025). "GBP2 has emerged as a significant regulator of chemoresistance and a potential therapeutic target in cancer treatment, addressing the major challenge of chemoresistance in achieving effective anticancer outcomes." (PMID 41181145, 2025). "A substantial body of literature indicates that GBP2 can exhibit both pro-tumorigenic and anti-tumorigenic functions in cancer." (PMID 41181145, 2025). "Studies on GBP2 and tumors have found that GBP2 is highly expressed in a variety of cancer patients and participates in the regulation of various regulatory factors during tumorigenesis." (PMID 37592228, 2023). "Next, we identified the differentially expressed genes between GBP2-high malignant cells (MES-like cancer cells) and other cells." (PMID 36186425, 2022). "Our result revealed a significant reduction in GBP2 expression inductal carcinoma breast tissues, compared with normal controls." (PMID 33211060, 2020). "Notably, high promoter methylation of GBP2 has been proposed as a potential biomarker for unfavorable outcomes in this cancer type." (PMID 40564939, 2025). "In addition, the pan-cancer analysis was performed to investigate the immunological role of GBP2 based on The Cancer Genome Atlas (TCGA) dataset, and the predictive value of GBP2 for immunotherapy was also examined in multiple public cohorts." (PMID 37784054, 2023). "GBP2’s immunological function in relation to other cancer types was unclear, nevertheless." (PMID 37784054, 2023). "GBP2, induced by IFN-γ, has been linked to a myriad of different cancer types as an oncogenic gene." (PMID 38288122, 2023). "GBP2 expression was elevated in various types of cancers including PAAD." (PMID 34026364, 2021). "Further study indicated the IRF1 seemed to play a key role in the transcriptional activation of interferon-inducible guanylate binding proteins (GBP1 and GBP2), which subsequently induces T-lymphocyte immune response against the cancer cell spreading and proliferation." (PMID 27806724, 2016). "However, the function of GBP2 differs in different cancer types." (PMID 37622120, 2023). "So, we guess GBP2 may play a critical role in cancer autophagy and needs more study to convince." (PMID 32269280, 2020). "So the promotermethylation of GBP2 may predict poor prognosis and invasiveness inbreast cancer." (PMID 33211060, 2020). "However, the targets and molecular mechanisms of GBP2’s regulation of cancer metastasis remain largely unknown." (PMID 29072687, 2017). "However, it still remains unclear whether GBP2 could act as biomarker in other cancers." (PMID 37784054, 2023).
cancer (continued). "The nine mRNAs are coding for proteins involved in cell cycle regulation (CDCA7L), modification of the T cell and B cell immune response (GBP2, GLUL, HERC5, PPP3CC), erythropoiesis (GBP2), and cell migration of cancer and hematopoietic cells (HERC5, HMHA1)." (PMID 28236054, 2017). "Although SLC11A1 shows excellent immunological prognostic value in other cancers, our K-M curves show better survival for high-expression groups of GBP2, P2RX7, and HCLS1 but not SLC11A1 in EC." (PMID 41007849, 2025). "GBP2, a GTP (guanylate-binding protein) superfamily member, plays a significant role in carcinoma." (PMID 35937997, 2022). "Except for GBP1 and GBP2, the role of other GBPs, including GBP5, in the malignant evolution of cancers, particularly TNBC, remains unclear." (PMID 33916322, 2021). "Gene set enrichment analysis (GSEA) of cancer hallmarks pathways in neutrophils showed upregulation of IFN-γ response genes in Group 1 compared with Group 2, which is confirmed by higher expression of IFN-γ–inducible guanylate binding proteins (Gbp2, Gbp4, Gbp6, and Gbp7)." (PMID 41165751, 2026). "Moreover, we also explored the expression of GBPs with cancer stage for HNSCC and we found GBP1/5/6 groups significantly varied, but GBP2/3/4/7 groups did not significantly differ." (PMID 32269280, 2020).
bacterial infection (10 papers, 2010 to 2025). "Based on existing studies, the overexpression of GBP2 can promote the activation of AIM2 during bacterial infection." (PMID 41199598, 2025). "GBP2 has been reported to induce cytoplasmic lysis and DNA release during bacterial infection and to promote the activation of melanoma infection factor 2 (AIM2) by the inflammasome." (PMID 36115937, 2022). "Collectively, these results demonstrate that GBP2 plays a critical role in the elevated caspase-11-induced immune response in Gate-16−/−Gabarap−/− macrophages in response to LPS transfection and bacterial infection." (PMID 33042141, 2020). "During bacterial infection, multiple mouse Gbps, human GBP2, and GBP5 support the activation of caspase‐1‐containing inflammasome complexes or caspase‐4 which trigger pyroptosis." (PMID 31268602, 2019). "Among these, GBP2, CXCL9, and IRG1 represent some of the pathways involved in the protective response: GBP2, a member of the GTPase family, drives macrophages toward an inflammatory state while combating bacterial infection through vacuole disruption and pyroptosis induction." (PMID 39819562, 2025). "Indeed, GBP2 and GBP5 appear to have important roles against viral and bacterial infections and to induce immune responses in mouse and humans." (PMID 35222365, 2022).
hematological diseases (2 papers, 2021 to 2025). "GBP2 has been implicated in several hematological disorders, where it influences disease progression and demonstrates diagnostic utility." (PMID 41181145, 2025). "In addition, we examined the changes in GBP2, BAK, and MCL-1 protein levels following exposure to the main chemotherapeutic agents used for the treatment of hematological malignancies, including doxorubicin, cytarabine, vincristine, etoposide, and interferon-γ." (PMID 34294680, 2021).
neurodegenerative disease (2 papers, 2023 to 2024). A disorder of the central nervous system characterized by gradual and progressive loss of neural tissue and neurologic function. "From this perspective, our study demonstrates that the downregulation of GBP2 can minimize neuronal damage caused by the induction of anti-inflammatory functions in activated microglia, providing evidence supporting GBP2 as a potential candidate molecule for alleviating neurodegenerative diseases." (PMID 38791092, 2024). "Decreased expression of pro-inflammatory genes, which are associated with neurodegenerative disease or astrocyte and microglia phenotypes Cd40, C1qB, Cd68, Cd45, Aqp-4, Il1α, Fkbp5, Ggta1, Cd16, H2-T23, and Serping1, was observed following C-32:6 treatment and C1qC, Tspo, and Gbp2 with FFA C-34:6." (PMID 37740008, 2023). "This study suggests that the GBP2 gene can be used as a therapeutic target biomarker for inflammation-related neurodegenerative diseases." (PMID 38791092, 2024). "Therefore, we aimed to investigate the role of the GBP2 gene in neurodegenerative diseases." (PMID 38791092, 2024).
brain disease (1 paper, 2024). "Based on the results of GBP2 expression in brain disease animal models, we evaluated whether this gene is expressed in microglial cells present in the brain." (PMID 38791092, 2024). "If molecular biological studies utilizing this gene and the actual expression of GBP2 in clinical patients are confirmed, this gene could become a highly valuable target for the prevention and diagnosis of brain diseases." (PMID 38791092, 2024).
infectious (1 paper, 2025). "Summary of GBP2 dysregulation, mechanisms, and functional roles in non-infectious human diseases." (PMID 41181145, 2025).
metabolic disease (1 paper, 2025). A congenital disorder (due to inherited enzyme abnormality) or acquired (due to failure of a metabolically important organ) disorder resulting from an abnormal metabolic process. "Moreover, GBP2 contributes to a range of systemic disorders, such as rheumatoid, neurological, and metabolic diseases, as well as hematological conditions and transplant-related pathologies." (PMID 41181145, 2025).
neurological diseases (1 paper, 2025). "GBP2 has been implicated in the pathogenesis of multiple neurological diseases." (PMID 41181145, 2025).
retinopathy (1 paper, 2024). "The expression of GBP2 was markedly downregulated in the retina of mice with oxygen-induced retinopathy, which was associated with pathological retinal angiogenesis." (PMID 39483475, 2024).
GBP2 also shares sentences with these, for which no sentence is quoted: psoriasis (2 papers); adenocarcinoma (1); atopic dermatitis (1); bacteremia (1); cerebral amyloid angiopathy (1); colitis (1); Creutzfeldt-Jakob disease (1); cystic fibrosis (1); diabetes (1); ductal carcinoma (1); endometrial carcinoma (1); eosinophilia (1); Gliosis (1); H1N1 virus infection (1); hemorrhage (1); Hepatitis (1); hepatitis C (1); HTLV Infection (1); ischemic stroke (1); liver fibrosis (1); lymph node metastasis (1); lymphoma (1); myeloid leukemia (1); non-small cell lung carcinoma (1); oligoastrocytoma (1); oligodendroglioma (1); Parkinson disease (1); pleural tuberculosis (1); Renal failure (1); respiratory diseases (1).
A further 5 diseases each share a sentence with GBP2 in 1 paper.